FGF23 (fibroblast growth factor 23)
Diseases named in the same sentence as FGF23 in open-access papers (continued):
Sharing a sentence is not in itself a finding about the gene and the disease.
Stroke (39 papers, 2013 to 2026). Sudden impairment of blood flow to a part of the brain due to occlusion or rupture of an artery to the brain. "Recent studies in patients show that high levels of FGF23 in the serum is associated with risk for stroke and dementia." (PMID 36650549, 2023). "Other studies have indicated that plasma FGF23 was associated with carotid atherosclerosis in patients who suffered from stroke as well as in the normal population." (PMID 33424930, 2020). "Several studies have demonstrated that an increased circulating FGF23 level was correlated with a higher risk and a poorer outcome for stroke." (PMID 33424930, 2020). "Accordingly, we examined the association of circulating 25(OH)D and FGF23 with incident cognitive impairment in the Reasons for Geographic and Racial Differences in Stroke (REGARDS) Study, a large cohort of black and white adults ≥45 years old." (PMID 27812184, 2016). "The objective of this study was to examine associations of 25(OH)D and FGF23 with incident cognitive impairment in the Reasons for Geographic and Racial Differences in Stroke (REGARDS) study, a cohort of black and white adults ≥45 years old." (PMID 27812184, 2016). "Moreover, elevated plasma FGF23 concentration has been implicated as a potential risk factor for stroke and intracerebral hemorrhage." (PMID 35928129, 2022). "Previous studies have demonstrated a positive association between FGF23 and stroke." (PMID 33424930, 2020). "FGF23 and risk of incident dementia and AD, excluding those with prior stroke." (PMID 30830941, 2019). "Interestingly, it was recently reported that high plasma FGF23 concentration is associated with the incidence of coronary disease cardioembolic stroke and stroke." (PMID 30595559, 2018). "Additionally, monitoring FGF-23 levels in the postoperative period could provide additional insights into the risk of complications, such as restenosis or recurrent stroke, allowing for tailored postoperative care." (PMID 40137447, 2025). "Since FGF23 is a modifiable risk factor, understanding this association may be an important step in reducing stroke incidences, stroke severity, and improving outcome after stroke." (PMID 30192823, 2018). "In summary, the findings from this study provide important insights into the potential clinical utility of FGF23 as a biomarker for CI and its association with VBI and stroke severity." (PMID 39096857, 2024). "Large epidemiological studies that investigated FGF23 levels in relation to CVD risk and mortality showed a strong association, especially with HF and stroke, but hardly any with CAD including MI." (PMID 34055103, 2021). "FGF-23 is also expressed within the brain and increased concentrations of FGF-23 have been associated with higher rates of stroke." (PMID 33306729, 2020). "We therefore planned a comprehensive assessment of renal dysfunction (including eGFR, albuminuria and FGF-23) in a prospective cohort of MRI-defined RSSI patients who also underwent control brain MRI at 15-months after stroke." (PMID 31659218, 2019). "In our study, participants in the top quartile of serum FGF23, compared to the bottom quartile, were more likely to have a history of stroke or CVD." (PMID 30830941, 2019). "Furthermore, the study showed that a high FGF23 level at admission was significantly related to more severe symptoms of CI as indicated by the National Institute of Health Stroke Scale (NIHSS) score on the 7th day after treatment (p < 0.001)." (PMID 39096857, 2024). "Additionally, the study analyzed the correlation between FGF23 levels and CI severity after treatment using the National Institute of Health Stroke Scale score." (PMID 39096857, 2024). "The therapeutic potential of FGF21 in stroke has been indicated by studies in animal models; however, the main limitation for a future translational application is the side effects of other related factors, such as FGF2 and FGF23, in clinical trials with stroke patients." (PMID 35207221, 2022).
Stroke (continued). "Therefore, although stroke is beyond the scope of this review, the harmful effects of FGF-23 on the vasculature deserve to be mentioned." (PMID 33767635, 2021). "Since excess phosphorus is thought to be a potential promoter of dystrophic calcification, FGF-23 concentrations may themselves lead to cerebrovascular disease states such as white matter disease, subclinical stroke, and clinical stroke." (PMID 33306729, 2020). "Atherosclerosis has been proposed as a mechanism by which FGF23 may promote cardiovascular events and stroke in these patients." (PMID 30808384, 2019). "A population-based study of stroke-free individuals found that FGF-23 is a risk factor for subsequent stroke independent of RD29, an association in CSVD with progressing vascular disease has not yet been reported." (PMID 31659218, 2019). "FGF23 has emerged as a novel biomarker for vascular disease including stroke." (PMID 30830941, 2019). "The Northern Manhattan study (NOMAS) prospectively assessed 2,525 individuals from a racially diverse population and concluded that elevated FGF23 conferred an overall risk of stroke and intracerebral hemorrhage independent of CKD." (PMID 30192823, 2018). "Even among individuals without CKD, elevated levels of FGF23 have been postulated to increase the risk of stroke." (PMID 30192823, 2018). "Our results complement and help explain previous findings suggesting that elevated FGF23 is associated with stroke and small vessel disease (SVD) independent of CKD." (PMID 30192823, 2018). "Observations by Wright and collaborators suggest that higher Fibroblast Growth Factor 23 (FGF-23)—a bone-derived hormone that regulates phosphorus homeostasis and that is often elevated in patients with CKD—is associated with increased risk of stroke even in patients with normal kidney function." (PMID 28152028, 2017). "Furthermore, the dose-response analysis demonstrated a potentially non-linear relationship between FGF23 and stroke, HF, and all-cause mortality." (PMID 36407457, 2022). "However, the researchers found no significant trends associating FGF23 levels in the highest quartile and the risk of MI and stroke." (PMID 34055103, 2021). "Therefore, FGF-23 could be an interesting biomarker in patients with CSVD-related stroke and might be related to their prognosis." (PMID 31659218, 2019). "In patients with coronary artery disease (CAD), high FGF23 levels were predictive for the composite endpoint of acute coronary syndrome (ACS), HF, stroke, and transient ischemic attacks." (PMID 35160052, 2022). "As elevation of FGF-23 usually precedes that of serum phosphorus, the authors hypothesized that FGF-23 might be elevated in some patients with normal kidney function as a response to increased dietary intake of phosphorus and might confer increased risk of stroke." (PMID 28152028, 2017). "Without monitoring of FGF-23 levels after carotid endarterectomy, it remains uncertain if this biomarker can predict restenosis, recurrent stroke, or long-term cardiovascular mortality." (PMID 40137447, 2025). "In conclusion, FGF-23 is likely signaling a worse health status in the FGF-23 upper-level group, since this group presented significantly more comorbidities (DM, CKD, previous MI and stroke) and more importantly, higher inflammation (higher CRP) and especially lower eGFR." (PMID 34297744, 2021). "Nonetheless, the effects of elevated FGF23 on brain health in non-stroke individuals have not fully been determined." (PMID 30192823, 2018).
coronary artery disease (38 papers, 2012 to 2025). "In the PEACE study, patients with stable coronary artery disease, low sαKlotho, and high FGF-23 levels had a significantly higher risk of cardiovascular death or rehospitalization for HF." (PMID 39941530, 2025). "Spearman correlation analysis was used to analyze the correlation between serum Homer1, SAH, Hcy, FGF23 levels and Gensini score, and multivariate unconditional Logistic regression was used to analyze the risk factors of coronary heart disease." (PMID 35546659, 2022). "Indeed, high levels of serum FGF-23 were associated with increased risk of coronary artery disease, in a cohort study involving 11,638 participants." (PMID 40137447, 2025). "Furthermore, in a cross-sectional study in patients with suspected coronary artery disease, serum FGF23 levels were associated with coronary calcification." (PMID 28974056, 2017). "Furthermore, FGF23 predicts risk of cardiovascular mortality and progression to congestive cardiac failure in patients with stable coronary artery disease." (PMID 25902817, 2015). "The aim of this study was to determine whether circulating FGF23 concentration is independently associated with the severity and extent of coronary artery disease in patients undergoing coronary angiography." (PMID 24015259, 2013). "Therefore, the analysis of the associations of FGF23 with coronary disease should be done separately from those patients with CKD, even with a minor impairment, since the decrease of Klotho expression is an early event in CKD." (PMID 22590632, 2012). "Elevated FGF-23 plasma concentrations were measured in patients with macroalbuminuric diabetic nephropathy, coronary artery disease, and other vascular diseases." (PMID 36437429, 2023). "For instance, in patients with stable coronary heart disease, low calcidiol plasma levels predict adverse prognosis in the presence of high FGF-23 levels." (PMID 37745119, 2023). "Elevated FGF23 levels are related to the development of coronary artery disease (CAD) and left ventricular hypertrophy (LVH) and myocardial ischemia (MI), stroke, and impaired immune response." (PMID 36440231, 2022). "Our findings also indicated the role of FGF-23 in predicting long-term outcomes in patients with suspected coronary artery disease." (PMID 34297744, 2021). "We have investigated the relationship of calcidiol (vitamin D metabolite) and FGF-23 plasma levels with the incidence of adverse outcomes in patients with coronary artery disease." (PMID 24748388, 2014). "Increased serum FGF23 concentrations were associated with adverse outcomes such as increased mortality in patients undergoing hemodialysis and mortality and cardiovascular events in patients with coronary artery disease (CAD)." (PMID 24015259, 2013). "In coronary artery disease, several trials have highlighted the relevance of FGF-23." (PMID 40137447, 2025). "A prior small study found that in patients with AMI complicated by CS without apparent pre-existing CKD FGF-23 levels were profoundly increased, showing more than 10-fold higher FGF-23 levels in patients with CS compared to patients with stable coronary artery disease (CAD)." (PMID 25528363, 2014). "Actually, FGF23 is associated with left ventricular hypertrophy, extent of atherosclerosis, endothelial dysfunction, and increased risk for mortality in CKD and in those with prevalent coronary disease." (PMID 23587028, 2013). "Prior studies have shown FGF-23 to have strong, independent associations with structural cardiovascular disease including LVH, coronary artery disease, and carotid intima-media thickness; cardiovascular events; and overall mortality in cohorts with prevalent CVD and all stages of CKD." (PMID 24148285, 2013). "The findings of some studies pointed out a positive relationship between blood FGF23 and LDL in patients with coronary heart disease." (PMID 37089720, 2023).
coronary artery disease (continued). "By contrast, FGF23 levels in patients with uncomplicated MI were not different from those in patients with stable coronary artery disease and have even been reported to decrease over the course of the first two days following an acute MI." (PMID 35160052, 2022). "In fact, we reported previously that Fibroblast Growth Factor (FGF-23), a phosphaturic hormone, predicts adverse cardiovascular outcome in patients with stable coronary artery disease (CAD) and T2DM, but not in patients without T2DM." (PMID 32294902, 2020). "Furthermore, regression analyses adjusted for mean arterial blood pressure, cardiac rhythm, coronary artery disease and congestive cardiac failure did not significantly impact the prognostic power of FGF23." (PMID 25902817, 2015). "However, other two studies reported that circulating FGF23 did not correlate with the development of incident coronary heart disease or with coronary artery calcification in patients without CKD or with normal renal function." (PMID 24015259, 2013). "Moreover, as noted in non-transplanted patients with CKD, higher FGF23 levels might be more consistently associated with cardiovascular volume overload complications (i.e., LVH and congestive heart failure) than with ischemic heart disease or atherosclerosis." (PMID 29874852, 2018).
dyslipidemia (38 papers, 2013 to 2026). "Here, we sought to define the role of metabolic syndrome-associated TNFα production in HFD-induced FGF23 formation." (PMID 29807981, 2018). "Levels of FGF23 were higher in participants with metabolic syndrome or at an increased risk of metabolic syndrome, indicating that FGF23 underlies cardiovascular risk via either phosphate or adverse lipid metabolism." (PMID 26241225, 2015). "Since FGF23 may be an indicator of the risk of metabolic syndrome, Klotho protein implies its role against metabolic diseases." (PMID 35053218, 2022). "FGF-23 is associated with dyslipidemia and may also promote atherosclerosis." (PMID 33748139, 2021). "Specifically, genes such as Fgf23 and Prkcb, which have been found to be highly expressed in individuals with metabolic syndrome, are among the targets." (PMID 39224599, 2024). "Further in vivo data are needed to support the physiological contributions of soluble Klotho protein independent to FGF23 in the mechanism of metabolic syndrome." (PMID 35053218, 2022). "Considering the fact that metabolic syndrome is the key risk factor for endometrial cancer, the examination of serum levels of FGF21 and FGF23 in endometrial cancer patients appears warranted." (PMID 32570721, 2020). "In humans, serum levels of FGF23 increase with higher body mass index and fat mass, and FGF23 levels were higher in individuals with metabolic syndrome." (PMID 32121294, 2020). "An energy-dense diet, which induces sequelae of the metabolic syndrome in humans and mice at least in part by enhancing pro-inflammatory TNFα formation, has recently been demonstrated to stimulate FGF23 production." (PMID 29807981, 2018). "While, FGF23 is inversely correlated with serum adiponectin level, thus it is possible that FGF23 is correlated to fat mass and related to dyslipidemia in CKD." (PMID 27471744, 2016). "Hypothesizing that the rising positive correlation between monocyte chemoattractant protein 1 (MCP1) and n-6 in stage 4 could be the cause, we previously explored FGF23 and MCP1’s roles in dyslipidemia and cardiovascular risk in CKD." (PMID 37762869, 2023). "FGF23 levels were higher in subjects with the metabolic syndrome compared with those without and associated with an increased risk of having the metabolic syndrome." (PMID 35053218, 2022). "Considering the fact that increased body mass, dyslipidemia, and increased leptin levels are factors involved in the pathogenesis of endometrial cancer, one should expect that patients with endometrial cancer should also present with higher levels of FGF23." (PMID 32570721, 2020). "In vivo models using ovariectomised or metabolic syndrome rats demonstrated that TT supplementation modulated key osteocyte-secreted factors, including sclerostin, dentin matrix protein 1, Dickkopf-related protein 1, fibroblast growth factor 23, and receptor activator of nuclear factor κB ligand." (PMID 41800088, 2026). "As a crucial component of the FGF23 signaling pathway, Klotho could play a pivotal role in the pathogenesis of age-associated disorders via the FGF-23–Klotho axis, including cardiovascular disease, renal dysfunction, and metabolic syndromes." (PMID 40737282, 2025). "Only few general population studies were performed and the following factors were associated with higher FGF23 levels: female sex, smoking, parathyroid hormone levels, GFR, C‐reactive protein, higher serum calcium levels, higher energy intake, lower iron intake, adiposity, and dyslipidemia." (PMID 38124483, 2024). "Given the present result, an anti-MCP1 strategy or a better understanding of the mechanism of immunotherapeutic agents may have potential therapeutic value to reduce the detrimental interrelationship between FGF23, dyslipidemia, and inflammation based on CV pathophysiological mechanisms in CKD." (PMID 37762869, 2023).
dyslipidemia (continued). "Recent studies demonstrate that FGF23 exacerbates left ventricle hypertrophy where αKlotho might not be expressed and elevated plasma FGF23 levels are associated with low body mass index and dyslipidemia in dialysis patients." (PMID 25873956, 2015). "In rats with metabolic syndrome, AT lowered RANKL, SOST, DKK-1 and fibroblast growth factor-23 level." (PMID 34790038, 2021). "The RKFD group had a higher prevalence of metabolic syndrome and central obesity; higher levels of eGFR, eGFRcr-cys, urine albumin-creatinine ratio (UACR), fasting glucose, insulin, HOMA-IR, and FGF-23; and lower levels of total cholesterol, LDL, and serum creatinine than the group without RKFD." (PMID 36671416, 2022).